GNRHR2 (gonadotropin releasing hormone receptor 2 (pseudogene))
Description:
Putative receptor for gonadotropin releasing hormone II (GnRH II) which is most probably non-functional.
Synonyms: GNRHR2P
Gene: Transcribed unitary pseudogene on chromosome 1 (145,919,344 to 145,925,233, forward strand). Ensembl gene ENSG00000211451.
Subcellular location: Cell membrane
Diseases named in the same sentence as GNRHR2 in open-access papers:
GNRHR2 is named in the same sentence as 7 diseases in open-access papers, as found by Europe PMC text mining. Sharing a sentence is not in itself a finding about the gene and the disease. The quoted sentences say what the papers report.
prostate carcinoma (3 papers, 2014 to 2023). A carcinoma that arises from epithelial cells of the prostate gland. "Photoaffinity labeling suggested that GnRH2 binds with high affinity to a protein in prostate cancer cells, implicating GnRHR2." (PMID 38260130, 2023). "Human prostate cancer cells treated with a GnRHR2 antagonist (Trptorelix-1) displayed increased mitochondrial dysfunction as well as autophagosome formation." (PMID 29312140, 2017). "Treatment with several GnRHR2 antagonists inhibited growth of human endometrial and ovarian cancer cells in vitro and in vivo via caspase 3-dependent mechanisms; a different GnRHR2 antagonist (SN09-2) induced apoptosis in prostate cancer cells." (PMID 29312140, 2017). "Therefore, GnRH2 and GnRHR2 may be involved in autocrine/paracrine regulation of prostate cancer progression." (PMID 38260130, 2023).
ovarian carcinoma (2 papers, 2017 to 2023). A malignant neoplasm originating from the surface ovarian epithelium. "Together, these findings suggest that GnRHR2 is functional in certain ovarian cancer cells." (PMID 38260130, 2023). "However, GnRH2 was the most potent competitor, indicating the presence of a functional 5-TM GnRHR2 in human ovarian cancer cells." (PMID 38260130, 2023). "Both immunoblotting of protein and photo labeling studies of cell membrane fractions from ovarian cancer cells (EFO-21, SK-OV-3) resulted in a band corresponding to the 5-TM GnRHR2 isoform (43-kDa)." (PMID 38260130, 2023). "GnRHR1 mRNA was downregulated by FSH or LH in most ovarian cancer cell lines but GnRHR2 expression was not examined." (PMID 38260130, 2023). "In SK-OV-3 ovarian cancer cells (expressing GnRHR2 but not GnRHR1), GnRH2 exhibited powerful anti-proliferative effects, unlike triptorelin, suggesting that GnRHR2 is mediating these effects." (PMID 38260130, 2023).
cervical cancer (1 paper, 2023). A primary or metastatic malignant neoplasm involving the cervix. "There is a critical need to better understand the potential function of GnRH2 and GnRHR2 in these cells since cervical cancer is the second most common cancer in women." (PMID 38260130, 2023).
endometrial carcinoma (1 paper, 2023). A malignant tumor arising from the epithelium that lines the cavity of the uterine body. "Co-expression of GnRH2 and GnRHR2 suggest an autocrine/paracrine role in endometrial cancers." (PMID 38260130, 2023). "Indeed, both low and high affinity binding sites for GnRH1 were detectable in human endometrial cancer cells, implicating the presence of GnRHR1 (high) and GnRHR2 (low)." (PMID 38260130, 2023). "Triptorelin, cetrorelix (pan GnRHR antagonist), and GnRH2 exerted anti-proliferative effects on endometrial cancer cells (Ishikawa, HEC-1A, and HEC-1B) that produce GnRHR1 and GnRHR2 transcripts." (PMID 38260130, 2023).
testicular cancer (1 paper, 2023). A primary or metastatic malignant neoplasm that affects the testis. "Although GnRH2 and GnRHR2 have been investigated in the regulation of many different reproductive cancers, there is a gap in our knowledge regarding the potential influence of GnRH2 and GnRHR2 as a therapeutic to treat testicular cancer." (PMID 38260130, 2023).
cancer (3 papers, 2017 to 2023). A tumor composed of atypical neoplastic, often pleomorphic cells that invade other tissues. "Indeed, many independent groups have reported evidence for a functional GnRHR2 in reproductive cancer cells." (PMID 38260130, 2023). "Recently, GnRH2 and GnRHR2 have been detected in reproductive cancer cells." (PMID 38260130, 2023). "However, GnRH2 and/or GnRHR2 are also expressed in other reproductive cancer cells (cervical, placenta), warranting further study." (PMID 38260130, 2023). "Furthermore, both GnRH2 and GnRHR2 are expressed in human reproductive tumors and are emerging targets for cancer treatment." (PMID 29312140, 2017). "Furthermore, both the GnRH2 and GnRHR2 genes are expressed in human reproductive tumors and represent emerging targets for cancer treatment." (PMID 29312140, 2017). "Thus, GnRH2 and GnRHR2 may be novel, unexploited cancer targets." (PMID 38260130, 2023).
GNRHR2 also shares sentences with these, for which no sentence is quoted: reproductive tumors (1 paper).